NFIB (nuclear factor I B)
Description:
Transcriptional activator of GFAP, essential for proper brain development. Recognizes and binds the palindromic sequence 5'-TTGGCNNNNNGCCAA-3' present in viral and cellular promoters and in the origin of replication of adenovirus type 2. These proteins are individually capable of activating transcription and replication.
Synonyms: NF1-B; CTF; NF-I/B; NFI-B; NFI-RED; NFIB2; NFIB3; HMGIC/NFIB; MACID
Tractability: PROTAC: ubiquitination databases record sites on it; its protein half-life has been measured.
Gene: Protein-coding gene on chromosome 9 (14,081,843 to 14,398,983, reverse strand). Ensembl gene ENSG00000147862.
Subcellular location: Nucleus
Subcellular location (Human Protein Atlas): Nucleoli fibrillar center; Nucleoplasm
Pathways (Reactome):
Gene expression (Transcription): RNA Polymerase III Abortive And Retractive Initiation; RNA Polymerase III Transcription Termination
Gene Ontology:
Molecular function: DNA binding; DNA-binding transcription activator activity, RNA polymerase II-specific; DNA-binding transcription factor activity, RNA polymerase II-specific; protein binding; RNA polymerase II cis-regulatory region sequence-specific DNA binding; sequence-specific double-stranded DNA binding; DNA-binding transcription factor activity
Biological process: brain development; negative regulation of miRNA transcription; positive regulation of DNA-templated transcription; positive regulation of transcription by RNA polymerase II; anterior commissure morphogenesis; chondrocyte differentiation; club cell differentiation; commissural neuron axon guidance; glial cell differentiation; lung ciliated cell differentiation; negative regulation of epithelial cell proliferation involved in lung morphogenesis; negative regulation of mesenchymal cell proliferation involved in lung development; principal sensory nucleus of trigeminal nerve development; regulation of transcription by RNA polymerase II; type I pneumocyte differentiation; type II pneumocyte differentiation; cell proliferation in forebrain; gene expression; regulation of DNA-templated transcription
Cellular component: fibrillar center; nucleoplasm; nucleus; cerebellar mossy fiber; chromatin
Genetic constraint (gnomAD): Loss-of-function variants: 10 observed, 56.54 expected, observed/expected ratio (o/e) 0.18, 90% interval 0.11 to 0.3. The upper end of that interval is the gene's LOEUF score, 0.3, which puts it in group 1 of 6, group 1 being the genes least tolerant of losing a copy. Missense variants: 443 observed, 592.26 expected, observed/expected ratio (o/e) 0.75, 90% interval 0.69 to 0.81. Synonymous variants: 249 observed, 209.29 expected, observed/expected ratio (o/e) 1.19, 90% interval 1.07 to 1.32.
Gene-disease validity (ClinGen):
ClinGen rates the evidence that NFIB causes each of these diseases.
syndromic complex neurodevelopmental disorder (autosomal dominant): Definitive. A disorder that involves more than one phenotype associated with the central nervous system, including but not limited to intellectual disability, autism, and seizures (epilepsy), and also a distinctive pattern of other features including dysmorphisms and/or congenital malformations.
Homologues: Orthologues: guinea pig NFIB (99% identical), chimpanzee NFIB (98% identical), dog NFIB (98% identical), pig NFIB (98% identical), rat Nfib (98% identical), mouse Nfib (98% identical), rabbit NFIB (98% identical), macaque NFIB (97% identical), tropical clawed frog nfib (93% identical), Drosophila melanogaster NfI (42% identical), Caenorhabditis elegans nfi-1 (35% identical). Paralogues in human: NFIA (62% identical), NFIC (60% identical), NFIX (59% identical).
Diseases named in the same sentence as NFIB in open-access papers:
NFIB is named in the same sentence as 137 diseases in open-access papers, as found by Europe PMC text mining. Sharing a sentence is not in itself a finding about the gene and the disease. The quoted sentences say what the papers report.
adenoid cystic carcinoma (39 papers, 2010 to 2025). A malignant tumor arising from the epithelial cells. "Studies in colorectal carcinoma have found high c-Myb expression to correlate with poor prognosis, and more recently the fusion of c-Myb and the transcription factor NFIB has been reported as a potential “hallmark” of adenoid cystic carcinomas." (PMID 20949095, 2010). "Several subtype can be associated with tumor-specific rearrangements, such as CRTC1::MAML2 in mucoepidermoid carcinoma, MYB::NFIB or MYBL1::NFIB in adenoid cystic carcinoma, and ETV6::NTRK3 in secretary carcinoma." (PMID 38358561, 2024). "Fusions among specific genes, namely myeloblastosis (MYB), MYB proto-oncogene like 1 (MYBL1), and nuclear factor I B (NFIB), have been related to adenoid cystic carcinoma." (PMID 37970205, 2023). "Recurrent gene fusions were primarily identified in prostate cancer (TMPRSS2::ERG) and adenoid cystic carcinoma (MYB::NFIB) in 1.74% (9/517) and 1.35% (7/517), respectively in the overall cohort." (PMID 31491926, 2019). "These include fusions of the ETV6 gene in secretory carcinoma (SC), MYB/MYBL1::NFIB in adenoid cystic carcinoma (AdCC), CRTC1/CRTC3::MAML2 in mucoepidermoid carcinoma (MEC), and EWSR1::ATF1 in hyalinizing clear cell carcinoma as the most frequent and best characterized gene fusions." (PMID 38217715, 2024). "Multiple entities in this group are defined by recurrent genetic alterations, such as MYB::NFIB and MYBL1::NFIB in adenoid cystic carcinoma, MAML2 fusions in mucoepidermoid carcinoma, NR4A3 upregulation by enhancer hijacking in acinic cell carcinoma, or ETV6::NTRK3 in secretory carcinoma." (PMID 37415052, 2023). "Recurrent translocations between MYB and NFIB occur in a high percentage of cases of adenoid cystic carcinoma (ACC), resulting in the expression of oncogenic MYB/NFIB fusion proteins." (PMID 38542205, 2024). "Recurrent fusion of the v-myb avian myelobastosis viral oncogene homolog (MYB) and nuclear factor I/B (NFIB) generates the MYB-NFIB transcription factor, which has been detected in a high percentage of individuals with adenoid cystic carcinoma (ACC)." (PMID 27213588, 2016). "No CYLD-mutant or CYLD-wildtype cases demonstrated the NFIB-MYB gene fusion typical of adenoid cystic carcinoma." (PMID 32892208, 2021).
breast carcinoma (24 papers, 2013 to 2025). "Significantly, ~46% NFIB-associated CNA loci detected in our system were also found in at least one of the four breast cancer cohorts, with a co-occurrence FDR less than 0.05." (PMID 37604829, 2023). "We showed that cancer-associated NFIB overexpression provokes genetic alterations that mimic the genomic aberrations in breast carcinomas and that NFIB-evoked genomic abnormalities dynamically evolve to confer growth advantage and therapeutic resistance." (PMID 37604829, 2023). "We show that cancer-associated NFIB overexpression elicits gene duplication and genetic alteration that mimic the genetic aberrance in clinical breast carcinomas." (PMID 37604829, 2023). "Significantly, cancer-associated NFIB overexpression provokes gene duplication and genomic alterations recapitulating the genetic aberrance in clinical breast cancer and empowering cancer cells to dynamically evolve growth advantage and drug resistance." (PMID 37604829, 2023). "Considering that NFIB has been implicated in skin stem cell maintenance and tumour growth in other cancer types, we addressed its effects on mammary tumours." (PMID 33751828, 2021). "We then repeated a series of biochemical and cellular experiments in two NFIBhigh breast cancer cell lines, ZR-75-1 and BT-474, to validate the interactions between NFIB and pre-RC, NFIB-dependent chromatin loading of pre-RC, and NFIB-associated cell cycle arrestment." (PMID 37604829, 2023). "Collectively, these observations indicate that at least in breast cancer cells, NFIB overexpression has a potential to cause genomic aberrations that could ultimately lead to carcinogenesis, supporting the role of NFIB in genome organization and replication initiation." (PMID 37604829, 2023). "For example, the overexpression of miR-205-5p was detected in patients with non-small cell lung cancer compared with controls, and miR-205-5p was significantly downregulated in estrogen receptor-positive breast cancer by targeting NFIB." (PMID 39133387, 2025). "hsa_circ_0010889 downregulation promoted miR-590-5p expression and importantly previous investigations found that circ_0069718 promotes breast cancer via upregulation of NFIB and targets miR-590-5p directly." (PMID 37540226, 2023). "To extend our observations to clinicopathologically relevant settings, we next analyzed the genomic aberrations observed in NFIB-overexpressing cells in reference to the genetic abnormalities in breast cancer samples." (PMID 37604829, 2023). "(ii) Previous studies have identified NFIB as a pro-metastatic gene and was highly upregulated in lung cancer and breast cancer." (PMID 35039066, 2022). "This outcome corroborates recent findings, pointing instead to the regulation of ERO1 by the transcription factor nuclear factor IB (NFIB) in breast cancer." (PMID 35853086, 2022). "Transcriptional factor nuclear factor IB (NFIB) is sufficient to enhance lung metastatic colonization via enhanced angiogenesis, thus revealing a targetable network that promotes breast cancer colonization." (PMID 33751828, 2021). "NFIB has been reported to play pivotal roles in the tumorigenesis of cancers, including gastric cancer, breast cancer, melanoma, and nonsmall cell lung cancer." (PMID 33981484, 2021). "NFIB overexpression discriminated between metastatic versus non‐metastatic TNBC breast cancer patient‐derived xenograft (PDX) models and NFIB, ERO1A and VEGFA were co‐overexpressed in these samples." (PMID 33751828, 2021). "Taken together, these data indicate that NFIB is a breast cancer metastasis transcriptional regulator which, through increased expression of ERO1A and VEGFA, promotes angiogenesis at the metastatic site." (PMID 33751828, 2021). "Next, analysis of NFIB mRNA expression levels from METABRIC and TCGA confirmed that NFIB expression is elevated in basal‐like breast cancer, according to PAM50 classification, and in iC10 by integrated cluster classification." (PMID 33751828, 2021).
breast carcinoma (continued). "NFIB is thus clinically relevant: it is preferentially expressed in the poor‐prognostic group of basal‐like breast cancers, and high expression of the NFIB/ERO1A/VEGFA pathway correlates with reduced breast cancer patient survival." (PMID 33751828, 2021). "Third, endogenous Nfib/NFIB overexpression was sufficient to evoke metastasis in non‐metastatic murine and human mammary cancer lines in both the orthotopic and experimental metastasis assays." (PMID 33751828, 2021). "Via an unbiased in vivo PB functional genetic screen, we have shown that NFIB induces mammary cancer metastatic progression and colonization." (PMID 33751828, 2021). "First, depletion of NFIB delayed mammary tumour growth and abrogated metastases in three different cell lines when using both the orthotopic and experimental metastasis assays." (PMID 33751828, 2021). "Using an inducible piggyBac (PB) transposon mutagenesis screen, we have shown that overexpression of the transcription factor nuclear factor IB (NFIB) alone is sufficient to enhance primary mammary tumour growth and lung metastatic colonization." (PMID 33751828, 2021). "We assessed angiogenesis by endothelial‐specific CD31 staining in sections of mouse mammary tumours and metastases from NFIB overexpression and KO models and observed higher and lower frequency of vascular structures than controls, respectively (Fig EV4E‐G)." (PMID 33751828, 2021). "We have collected functional and mechanistic evidence that NFIB is a mammary cancer metastatic transcriptional regulator." (PMID 33751828, 2021). "The results of these functional assays demonstrate the importance of NFIB in mammary cancer metastatic colonization." (PMID 33751828, 2021). "MiR-205 has been also demonstrated to negatively regulate the oncogene Nuclear factor I/B (NFIB) in ER+ breast cancer." (PMID 33375067, 2020). "In the present study, high expression of NFIA, NFIB and NFIX was significantly associated with improved prognosis in breast cancer." (PMID 32219034, 2020). "NFIB was significantly downregulated in 22 unique analyses across different breast cancer subtypes in 10 different databases including TCGA, Curtis, Ma 4, Zhao, Turashvili, Sorlie, Richardson2, Sorlie2, Perou and Gluck." (PMID 32219034, 2020). "To confirm the co-amplification of ERBB2 and NFIB overexpression and to support the clinicopathological significance of this co-amplification in breast carcinogenesis, we collected a panel of breast cancer cell lines for western blotting analysis of the expression of NFIB." (PMID 37604829, 2023). "It will be interesting to determine whether mammary-enriched ELF5, STAT5, NFIB, and GR are also recruited in these super-enhancers and whether differential molecular recruitment to super-enhancers determines the different breast cancer subtypes." (PMID 36232979, 2022). "Similarly, the known EMT regulator NFIB was identified in an inducible piggyBac transposon mutagenesis screen to promote breast cancer metastasis via the NFIB-ERO1A axis." (PMID 36497409, 2022). "Notably, we found that high expression of NFIB and the combined signature of ERO1A and NFIB in patients with breast cancer of the basal‐like subtype were predictive of decreased distant metastasis‐free survival and/or overall survival." (PMID 33751828, 2021). "Emerging evidence has demonstrated that NFIB could not only participate in normal somatic development, it also acted as an oncogene and involved in tumorigenesis of several cancers, including osteosarcoma, glioma, astrocytoma, gastric cancer, breast cancer." (PMID 33013202, 2020).
breast carcinoma (continued). "Altogether, these findings show that Ero1l/ERO1A expression is increased in Nfib/NFIB‐overexpressing models and suggest that the NFIB‐ERO1A axis is critical for metastatic colonization in breast cancer." (PMID 33751828, 2021). "NFIB is expressed preferentially in basal‐like breast cancers and is a potential prognostic factor in TNBC human breast cancer, as observed in previous reports." (PMID 33751828, 2021). "On the one hand, NFIB acts as a tumor‐promoting gene in small‐cell lung cancer (SCLC) 12, 13, 14, 15, melanoma 16, breast cancer 17, 18, and colon cancer." (PMID 29577671, 2018). "We then retrieved genes co-amplified with NFIB from 4 breast cancer cohorts, including 2051 patient samples in METABRIC (Molecular Taxonomy of Breast Cancer International Consortium) and ~1000 patient samples in TCGA (The Cancer Genome Atlas) through cBioPortal63–65." (PMID 37604829, 2023). "The results showed that higher NFIB expression was correlated with a worse distant metastasis-free survival (DMFS) as well as with relapse-free survival (RFS) of breast cancer patients of HER2+ subtypes, but not of other subtypes." (PMID 37604829, 2023). "Thus, NFIB appears to be sufficient to induce metastasis when overexpressed in non‐ (HR1) and low‐ (SUM159PT) metastatic mammary cancer lines." (PMID 33751828, 2021). "For example, NFIB, the most well studied NFI transcription factor, might be oncogenic in SCLC, melanoma, and breast cancer, but likely functions as a tumor suppressor in NSCLC, osteosarcoma, glioma and glioblastoma." (PMID 32219034, 2020). "And the correlation between BCL6, NFIB and SMAD3 is only present in CRPC tumor tissues and not in CSPC tumor tissues or other adenocarcinoma tissues (e.g., esophageal cancer and breast cancer)." (PMID 40470696, 2025). "While the correlation analysis supports the role of NFIB in HER2+ breast carcinogenesis, it does not exclude its function in other subtypes of breast cancer or other cancers considering the complex molecular signature and tumor heterogeneity in those cases." (PMID 37604829, 2023).